EGFR (epidermal growth factor receptor)
Diseases named in the same sentence as EGFR in open-access papers (continued):
Sharing a sentence is not in itself a finding about the gene and the disease.
tumor (continued). "Based on these results we may conclude that patient #12, who contains an EGFR L858R mutation as well as a PIK3CA C420R mutation in the tumor DNA, may be less responsive to EGFR or PIK3CA inhibitors, but this has not yet been confirmed by clinical studies." (PMID 26068980, 2015). "Eighty patients with tumor harboring EGFR gene mutations were also excluded." (PMID 26416458, 2015). "For example, tumor cells expressing mutated EGFR may have different thresholds of changes in 18 F-FDG uptake at early time points." (PMID 25888731, 2015). "Somatic mutations in cancer driver genes, tumor suppressors, and amplified oncogenes such as EGFR, RAS, BRAF, MYC, isocitrate dehydrogenase (IDH), and fumarate hydratase (FH) have been shown to be linked to specific alterations in metabolic activity in cancer cells (11, –, 14)." (PMID 26023239, 2015). "Likewise, mutations in NF1, a suppressor of RAS activity, were negatively associated with EGFR mutations in GBM, a tumor type in which activating deletions in the extracellular domain of EGFR are typically found." (PMID 26047463, 2015). "Human epidermal growth factor receptor-2 (HER2), a known proto-oncogene located on the long arm of human chromosome 17 (17q12), is a member of the epidermal growth factor receptor (EGFR) superfamily associated with tumor cell proliferation, apoptosis, adhesion, migration, and differentiation." (PMID 25402957, 2015). "Tumor grade seemed to be significantly associated with EGFR mutation frequency; however, this variable was documented for a little number of patients, mainly due to the limited amount of tissue available for diagnosis, and was therefore not included in the multivariate analysis." (PMID 26599344, 2015). "There is an ongoing debate on whether the expression of immunomarkers, e.g., TTF1 on tumor cells could help to predict the EGFR mutations in AC patients." (PMID 25086987, 2015). "We describe Smarcb1 dependent constitutive phosphorylation of the EGFR, which is also transcriptional elevated in Smarcb1 deficient cells and demonstrate that inhibition of the EGFR/ERBB signaling pathway inhibits proliferation of Smarcb1 deficient tumor cells." (PMID 26370283, 2015). "Perspectively, screening of ctDNA for EGFR ectodomain mutations may be helpful in monitoring patients for resistance-mediating tumor subclones." (PMID 26059438, 2015). "Thus, other sensitive and noninvasive approaches for evaluating EGFR gene mutation status using surrogate tumor tissues to predict EGFR-TKI efficacy are still needed." (PMID 26047516, 2015). "Importantly, the tumours that transformed to SCLC harboured the original activating EGFR mutation, suggesting direct evolution from the initial cancer, rather than a distinct, second primary cancer." (PMID 25758528, 2015). "It has been reported that tumours harbouring a G13D mutation in the KRAS gene might be sensitive to EGFR-inhibitors." (PMID 26386973, 2015). "We tested the hypothesis that EGFR density, vascular density, and tumor proliferation are directly associated with tumor cetuximab-IRDye800CW fluorescence localization and intensity." (PMID 26120042, 2015). "In many cases, the target is a protein with activating mutations that is present only in tumor cells, facilitating the specificity of the therapy (for example, Braf-mutant melanomas, EGFR-mutant lung cancer), allowing profound inhibition of the target before the emergence of side effects." (PMID 25887735, 2015). "Likewise, the MMP-13 staining index of EGFR mutated (n = 3) and EGFR wild-type (n = 22) tumors was comparable for both in tumor cells and fibroblasts (p = 1 for tumor cells and p = 0.23 for fibroblasts; Fisher’s exact test)." (PMID 26193700, 2015).
tumor (continued). "Evaluation of 245 NSCLC slides showed precise automated tumor annotation of cases using Tissuemark, strong concordance with manually drawn boundaries and identical EGFR mutational status, following manual macrodissection from the image analysis generated tumor boundaries." (PMID 26317646, 2015). "A strength of this research is the low rate of EGFR mutation-positive tumours in our population." (PMID 26137881, 2015). "EGFR is a transmembrane tyrosine kinase receptor, whose overexpression causes gene amplification and mutation, leading to cell proliferation, cell survival, ability of invasion and metastasis, tumor-induced neoangiogenesis." (PMID 26361513, 2015). "In the present study, we have demonstrated the presence of the T790M mutation in all tumor specimens obtained from NSCLC patients with activating EGFR mutations regardless of whether the samples were obtained before or after EGFR-TKI treatment." (PMID 26015401, 2015). "Tumor cell proliferation and angiogenesis, which may be implicated in radioresistance, require the interaction between EGFR and VEGF and downstream signaling of the PI3K/Akt pathway." (PMID 26569225, 2015). "In addition, the simultaneous expression of EGFR and its ligands in tumor and adjacent lung tissues was associated with lower overall and relapse-free survival in NSCLC patients." (PMID 26634172, 2015). "In particular, a better OS rate occurred in patients with good ECOG performance status (14 vs. 4 months, p = 0.000), and the OS was marginally better among patients who had never smoked (14 vs. 9 months; p = 0.088) or those with a mutated EGFR tumor (10 vs. 17 months, p = 0.098)." (PMID 26392415, 2015). "For example, EGFR tyrosine kinase inhibitors (TKIs), such as gefitinib and erlotinib, are approved for patients with mutations in the EGFR gene; it is now widely accepted that response to EGFR TKIs is greater in patients with tumours harbouring EGFR mutations compared with wild-type EGFR oncogenes." (PMID 26338018, 2015). "Future studies are warranted to explore whether Mer expression and/or activation status in tumor tissues would be correlated with the response of patients with NSCLC harboring EGFR mutation to erlotinib or other EGFR-targeted agents." (PMID 25826078, 2015). "However, in the blood samples, only 1 patient was found to harbor EGFR mutation (3.1%) while the EGFR mutation rate tested in the tumor tissue was 47.1% (24/51)." (PMID 26216071, 2015). "Hypotheses to explain anti-EGFR resistance include the acquisition of oncogene activating mutations, activation of alternative signaling growth pathways, or modifications in tumor composition." (PMID 26437222, 2015). "This led to the question whether increased activation of KRAS signaling by KRAS mutations can be modulated, thereby making KRAS mutated tumours sensitive to EGFR inhibitor therapy." (PMID 26386973, 2015). "Next, we tested whether enrichment PCR-UDP and UDP can detect rare EGFR mutations within the same FFPE tumor tissues, and correlated these results with those obtained in the same tissues by PNA-mediated real-time PCR clamping." (PMID 25915533, 2015). "However, invariably after 6-12 months, the tumor becomes resistant to therapy, associated with additional genomic changes especially a T790M EGFR mutation." (PMID 25528770, 2015). "EGFR mutations were associated frequently with lepidic and acinar patterns and infrequently with mucinous patterns in cases where the histologic pattern predominated in >10% of the tumor area." (PMID 25760072, 2015). "In addition, the knowledge that nuclear EGFR is associated with resistance to different cancer therapeutics and correlates with worse survival in some tumor types motivate the seek for an alternative to target this nuclear receptor." (PMID 25991665, 2015).
tumor (continued). "This suggests that consideration of alterations in EGFR mutation status during tumour progression is important, and repeat mutation testing may, therefore, be appropriate during clinical management of patients." (PMID 26338018, 2015). "And it may be difficult to obtain enough DNA for EGFR mutation test if biopsy tissue lacks tumor cells." (PMID 26448936, 2015). "In addition, the tumor cells harboring HER2YVMA mutations have been demonstrated to be resistant to reversible EGFR-TKIs such as gefitinib and erlotinib, while they remain sensitive to HER2 and dual EGFR/HER2 inhibitors." (PMID 26102513, 2015). "In a previously published case report, members of our research group had used high doses of gefitinib when it was still approved for use in the United States to treat such a NSCLC patient with leptomeningeal metastases and a known somatic exon 19 deletion mutation in his tumor EGFR." (PMID 25784657, 2015). "In contrast to adenocarcinoma of the lung or colon where mutations in EGFR or K-RAS are the markers clearly predicting the sensitivity of tumor cells to EGFR inhibitors, the presence of VHL mutations is not a clear indication for the use of VEGF/VEGFR inhibitors or other antiangiogenic drugs." (PMID 26500709, 2015). "EGFR mutations could be predicted by the necrosis/contrast enhancing (AUC = 0.68, p = 0.001) ratio and contrast enhancing/tumor bulk (AUC = 0.68, p = 0.001) ratio." (PMID 26337765, 2015). "In light of the new findings that EGFR amplification is associated with amplification of other driver oncogenes we hypothesized that these oncogenes may become the new drivers of tumor progression." (PMID 26328271, 2015). "The routine materials for EGFR mutation analyses are tumor tissues acquired by surgery or biopsy." (PMID 26227959, 2015). "Inter-group analysis of the FDGmax uptake at day 1 relative to baseline showed that one dose of Pan-HER therapy caused a significantly greater reduction in tumor metabolism than treatment with the vehicle (p ≤ 0.001), EGFR (p ≤ 0.01) or HER2 (p ≤ 0.01) antibody mixtures alone." (PMID 26460961, 2015). "One explanation of this could be that TKIs are most efficacious when targeting tumor cells that express mutations in exons 19 and 21 of the EGFR kinase domain, which has been identified in various cancer types but has not yet been elucidated in GBM." (PMID 25688333, 2015). "Also, only TMS but not DMU-212 has selectivity on G-R NSCLC cells, making it more promising with a wider therapeutic window between tumor with EGFR mutation and normal lung tissue with wild-type EGFR." (PMID 26542098, 2015). "Chemotherapy may selectively kill and inhibit mutant clones within the tumor, whereas wild type clones may proliferate, altering the relative proportion of EGFR-mutated/EGFR-wild type cells within the tumor mass." (PMID 26308162, 2015). "Univariate analysis with respect to SCC demonstrated that tumor density, EGFR expression, and vascular density were directly associated with MFI (P < 0.05) in all three dosing cohorts, whereas Ki67 and MFI were significantly associated (P < 0.05) at the lowest dose concentration group (2.5 mg/m2)." (PMID 26120042, 2015). "Response to erlotinib is highly dependent on the mutation status of EGFR in tumour tissue." (PMID 25743274, 2015). "Notably, the combination of linsitinib and dasatinib induces apoptosis in H1975, PC-9R, and PC-9/ER cells with acquired resistance to EGFR TKIs in vitro and causes substantial tumor shrinkage in mice harboring H1975 xenograft tumors in vivo." (PMID 26041671, 2015). "Afatinib has anti-tumor effect in NSCLC with EGFR mutations." (PMID 25537503, 2015). "EGFR (Kin-1) and its family members are often overexpressed in many solid tumoursincluding breast, lung, head and neck, prostate and colon and are associated withaggressive tumour progression and poor prognosis." (PMID 25658745, 2015).
tumor (continued). "Moreover, recent analysis has shown that multiple EGFR point and deletion mutations can be expressed in the same tumor at different allelic frequencies." (PMID 24292886, 2014). "The tumor was found to have two EGFR mutations, G719S and L747S." (PMID 24396447, 2014). "The evidence from our previous studies and others suggested that BTC play a critical role in the development of lung inflammation through the regulation of the cytokine secretion pattern and tumor cell progression through EGFR ligation, possibly associated with the over-production of CXCL8." (PMID 24629040, 2014). "One common hypothesis of Cetuximab-resistance is EGFR or downstream molecular mutation within tumor cells, such as acquired EGFR ectodomain mutation S492R." (PMID 24618737, 2014). "A total of 60 tumor samples were suitable for EGFR mutation analysis." (PMID 25410981, 2014). "Afatinib also shows activity against cancers resistant to first-generation EGFR inhibitors due to certain activating EGFR mutations, secondary EGFR mutations such as T790M or tumours expressing other ErbB family receptors activated by drug-induced reprogramming of signalling pathways." (PMID 24643470, 2014). "The interaction of primary tumor location and KRAS mutations suggests that primary tumor location might be an additional biomarker for EGFR-mABs." (PMID 24816724, 2014). "Since EGFR is overexpressed in a variety of tumors, the accumulation of radiolabeled cetuximab in the tumor cells could serve as complementary diagnostic tool." (PMID 24603603, 2014). "However, since these studies used qualitative detection of EGFR mutations, it is impossible to quantitatively evaluate the abundance of EGFR mutations in the primary tumor and metastases." (PMID 24398248, 2014). "In this study, we show that the combination of a selective MEK inhibitor and a PI3K/mTOR inhibitor is effective against tumor cell lines refractory to gefitinib by three different mechanisms: an EGFR gatekeeper T790M mutation, MET amplification, and KRAS/PIK3CA mutation." (PMID 24939055, 2014). "It is worth noting that EGFR and K-Ras mutations are rarely found in the same tumor, suggesting that they may drive functionally different carcinogenetic processes." (PMID 25300933, 2014). "In addition, we show the relationship between tumor volume and amount of EGFR mutations, and discuss mechanisms of release of tumor derived DNA into peripheral blood." (PMID 25462870, 2014). "The overall concordance of EGFR mutation status in plasma and tumour biopsy was 91% (179/196)." (PMID 24773774, 2014). "This was the case with the EGFR TKIs, where the biomarker of interest was initially thought to be EGFR protein expression but pre-specified subgroup analysis confirmed a greater benefit for this therapy in patients with the presence of EGFR mutation in the tumor." (PMID 25295228, 2014). "A total of 102 out of 136 patients provided tumor samples for EGFR mutation analysis." (PMID 24885205, 2014). "Her-2 and epidermal growth factor receptor (EGFR) are tumor-associated markers for detecting CTCs." (PMID 25521853, 2014). "We found that HM90822B significantly inhibited the expression of XIAP and survivin, reduced cell growth in NSCLC cells, especially cells harboring mutated EGFR, and resulted in tumor regression in xenograft mice originated with these cells, such as HCC827 and PC-9 cells." (PMID 25321484, 2014). "We secondly tested whether EGFR CN increase could explain why EGFR mutation assessment, remain possible for cases with very few tumor cells." (PMID 24885034, 2014).
tumor (continued). "However, the loss of contact-inhibition is a hallmark of malignant tumor phenotypes and it is likely that the role of EGFR is markedly different in malignant vs. benign cells." (PMID 25272226, 2014). "Thus, the allelic ratio of each specimen depends not only on the tumor cell content but also on the EGFR copy number and on the number of mutated allele in tumor cells." (PMID 24885034, 2014). "Recently, it has been suggested that, in addition to RAS mutations, the primary tumor location might play a crucial role for efficacy of EGFR-mABs." (PMID 24816724, 2014). "Although the mutation status of EGFR or other key genes in these patient tumor-derived cells is unknown, the status of KRAS, PIK3CA, or PTEN was mostly wild type." (PMID 25466244, 2014). "The biological significance of multiple coincident EGFR deletion mutations in the same tumor remains unclear." (PMID 24292886, 2014). "Because EGFR-mutated tumours often remain sensitive to ErbB targeting agents beyond progression, thus allowing re-introduction of these agents in later lines of therapy, it is important to test whether chemotherapy impacts on the sensitivity to these drugs." (PMID 24643470, 2014). "However, following the detection of the T790M EGFR substitution mutation in the tumor cells, the patient exhibited poor curative effect when treatment with gefitinib was continued." (PMID 25120654, 2014). "The presence of an activating EGFR mutation in the tumor varies among different races." (PMID 25563355, 2014). "Only 60% of this preselected population had EGFR mutation-positive tumours." (PMID 25100284, 2014). "As expected in Caucasians, the frequency of EGFR mutated tumor was 15%." (PMID 24885034, 2014). "One hypothesis is that the initial tumor includes cells carrying resistance mutations that exist prior to EGFR-TKI therapy." (PMID 24396447, 2014). "As the blood mirrors the entire tumour burden, the use of plasma DNA for EGFR mutation might be more precise and informative." (PMID 24773774, 2014). "Indeed, overexpression as well as mutations in the EGFR gene was shown to directly correlate with tumor radioresistance and poor clinical prognosis." (PMID 24141602, 2014). "Specific uptake of molecular biomarkers can be achieved using radiolabeled targeting agents such as antibodies, directed against tumor-associated antigens like epidermal growth factor receptor (EGFR), human epidermal growth factor receptor 2 (HER2), and many others." (PMID 24991539, 2014). "In addition, a detection system for human EGFR mutations with plasma DNA can be used to assess tumor progression." (PMID 25462870, 2014). "In April 2009, the American Society of Clinical Oncology (ASCO) recommended that patients with metastatic CRC who are candidates for EGFR inhibitors have their tumor tested for KRAS mutations, and that those with a KRAS mutation in codon 12 or 13 not receive anti-EGFR treatment." (PMID 24788807, 2014). "EGFR mutation detection was performed in 109 patients with tumor tissues." (PMID 25098700, 2014). "Interestingly, we had detectable EGFR mutations in 18/23 contributive samples with ≤ 10% of tumor cells." (PMID 24885034, 2014). "EGFR activation is associated with cell apoptosis, proliferation, angiogenesis, invasion, and metastasis, which plays an important role in carcinogenesis and tumor progression in human epithelial cancers, including NSCLC." (PMID 25441176, 2014). "At the opposite, for half of the samples, tumor loci showed different EGFR copy number that may affect mutation detection cut-off." (PMID 24885034, 2014). "Cytological samples, such as fine-needle aspirates, bronchial brushings, serum, plasma, circulating tumour cells and pleural effusion samples have all been used for EGFR mutation testing, but are considered less reliable because of heterogeneity of tissue samples and sparse cellularity." (PMID 25100284, 2014).